CD4 (CD4 molecule)
Diseases named in the same sentence as CD4 in open-access papers (continued):
Sharing a sentence is not in itself a finding about the gene and the disease.
hepatocellular carcinoma (230 papers, 2008 to 2026). A malignant tumor that arises from hepatocytes. "While HIV targets CD4+ T cells, the liver with its associated diseases (cirrhosis and hepatocellular carcinoma) is targeted by HBV." (PMID 40003989, 2025). "Hepatocellular carcinoma studies implemented this strategy, engineering multi-epitope/multi-target/multi-allele vaccines to activate CD4+/CD8+ T cells." (PMID 40861816, 2025). "While HIV targets CD4+ T cells, the liver, along with its associated diseases (cirrhosis and hepatocellular carcinoma), is targeted by HBV." (PMID 40003989, 2025). "Knockdown of macroH2A1, an epigenetic regulatory histone variant, in hepatocellular carcinoma cells promoted chemoresistance and CD4+CD25+FOXP3+ Treg cell activation." (PMID 39232704, 2024). "Predominant inflammatory immunological patterns as well as the depletion of CD4+ T cells during nonalcoholic fatty liver disease (NAFLD) are reported to be associated with the progression of hepatocellular carcinoma (HCC)." (PMID 36428596, 2022). "To further validate the association between macrophage, naïve CD4 + T cell and Treg cell in liver carcinoma, we estimated the translational level of their marker genes using immunohistochemistry." (PMID 36221095, 2022). "In this study, MMP9, SPP1, HAGLR, LINC02202, and RP11-598F7.3 are considered as potential diagnostic biomarkers for hepatocellular carcinoma, and CD4+ memory resting T cells and CD8+ T cells are believed to be involved in HCC immune control." (PMID 35027925, 2022). "CD8 were significantly associated with survival from hepatocellular carcinoma (p=0.002), while low-expression of CD4/CD8 just showed a trend towards patient survival (p=0.100)." (PMID 32742491, 2020). "In a recent study, NAFLD induced by an MCD diet caused a loss of CD4+ T lymphocytes and promoted the development of hepatocellular carcinoma in inducible liver-specific MYC oncogene transgenic mice." (PMID 28852648, 2017). "These pre-malignant senescent cells are usually eliminated by the CD4-positive (CD4+) T cell-mediated adaptive immune response, but impairment of this system by CD4+ T cell deficiency results in the development of hepatocellular carcinoma." (PMID 27311402, 2016). "In particular, a high CD8+/Foxp3+CD4+ T cells ratio has been associated with favorable disease outcome in ovarian and hepatocellular carcinoma patients and with a poor prognosis in subjects affected by head and neck cancer." (PMID 26604855, 2015). "However, information on the CD4+/CD8+ ratio in CCA is limited, although an increase in the CD4+/CD8+ ratio has been associated with an improved prognosis in hepatocellular carcinoma following transarterial chemoembolization (TACE)." (PMID 40006012, 2025). "Hepatocellular carcinoma (HCC) is the second leading cause of cancer-related death worldwide, and CD4+ T lymphocytes can inhibit hepatocarcinogenesis and mediate tumor regression." (PMID 36700197, 2022). "More recently, close proximity of intrahepatic CD8+ T cells to Tph-like CD4+ T cells that produced IL-21 and CXCL13 was associated with reversal of exhaustion after immune checkpoint inhibitor blockade in hepatocellular carcinoma." (PMID 40956619, 2025). "Macrophage-naive CD4 + T cell interaction significantly affects the cancerous state in liver carcinoma." (PMID 39981232, 2025). "The percentage of LAP+CD4+ T cells in peripheral blood of hepatocellular carcinoma patients was reported to be correlated with tumor size." (PMID 40053558, 2025). "BTLA expression is significantly upregulated on circulating and tumor-infiltrating CD4+ T cells in hepatocellular carcinoma." (PMID 40463377, 2025). "Nevertheless, there is no research on the correlation between Macrophages M0, B cells naive, Monocytes, T cells CD4 memory resting and hepatocellular carcinoma." (PMID 38297250, 2024). "Currently, PB has been reported to inhibit the progression of hepatocellular carcinoma by suppressing NF-κB activation in CD4+ T cells." (PMID 39881875, 2024).
hepatocellular carcinoma (continued). "The expression of CDC6 has a positive correlation with the tumor purity and the infiltration level range of B cells, CD8+T cells, CD4+T cells, macrophages, neutrophils, and dendritic cells in hepatocellular carcinoma (HCC) tissues." (PMID 39684684, 2024). "PLAU is associated with six types of infiltrating immune cells in hepatocellular carcinoma (LIHC), including CD4+ T cells, neutrophils, CD8+ T cells, macrophages, B cells, and dendritic cells." (PMID 39744064, 2024). "In hepatitis B virus (HBV)-associated hepatocellular carcinoma (HCC), Tim-3+ CD4+ T cells express aging markers and their proliferative capacity and effector function are decreased compared with Tim-3− T cells." (PMID 39539619, 2024). "An increased CD4+ T cells-to-Tregs ratio after tivozanib treatment has further been reported to significantly improve the prognoses of patients with hepatocellular carcinoma." (PMID 37263638, 2023). "CD4+ CTLs have been previously identified in human with chronic viral infections, hepatocellular carcinoma, and autoimmune fibrotic diseases, including IgG4-RD." (PMID 37624388, 2023). "CD4, UGT2B7, and CYP3A4 were selected as the potential diagnostic biomarkers of non-alcoholic fatty liver disease–hepatocellular carcinoma." (PMID 37089050, 2023). "In conclusion, this study reveals the crucial role of macrophage-naïve CD4 + T cell interaction in the immunosuppressive microenvironment of primary liver carcinoma." (PMID 36221095, 2022). "CDKN2A expression was positively correlated with infiltrating levels into CD8+ T cells, CD4+ T cells, and neutrophils in hepatocellular carcinoma." (PMID 35937995, 2022). "In this study, we conducted a comprehensive analysis of the prognostic value of CD4+ conventional T cells-related lncRNAs in hepatocellular carcinoma based on single-cell RNA sequencing data." (PMID 36700197, 2022). "This study reveals the crucial role of macrophage-naive CD4 + T cell interaction in the immunosuppressive microenvironment of liver carcinoma." (PMID 36221095, 2022). "CCNB1 and BIRC5 have been reported to be related to the immune infiltration of hepatocellular carcinoma, and their expressions are positively correlated with the infiltration levels of CD4 + T cells and dendritic cells, respectively." (PMID 36175893, 2022). "For instance, CD4+CD25+ regulatory T cells in the liver of patients with hepatocellular carcinoma were notably increased." (PMID 36185217, 2022). "Antitumor activity mediated by cytotoxic CD4 T cells was also shown in a model of hepatocellular carcinoma treated with a DC vaccine and interleukin-12 (IL-12)." (PMID 35572552, 2022). "Considering the limited therapy available for primary liver carcinoma, we predicted potential sensitive drugs based on macrophage-naïve CD4 + T cell interaction." (PMID 36221095, 2022). "Studies have pointed out that the expression levels of PLOD1-3 in hepatocellular carcinoma are positively correlated with the activity of infiltrating immune cells, including macrophages, neutrophils, CD4+ T cells, and dendritic cells." (PMID 35265665, 2021). "CD4 cells have been mainly associated with pathologic roles during NAFLD including in fibrosis and hepatocellular carcinoma (HCC)." (PMID 34830072, 2021). "Recently, CD4+CD25+ Foxp3 Treg has been highlighted as playing a key immunosuppressive role in the cellular subpopulation of the tumor microenvironment in hepatocellular carcinoma (HCC), which is critical in both the development and spread of HCC." (PMID 34858499, 2021). "Patients with common NADCs were at relatively high CD4 level, while hepatic carcinoma was an exception (the CD4 median was 153.5/μL)." (PMID 34934097, 2021). "HCC is one of the most common and aggressive human malignancies and CD4+CD25++Treg promote hepatocellular carcinoma invasion via TGF-β1 dependent mechanisms." (PMID 33995362, 2021).
hepatocellular carcinoma (continued). "The balance between anti-tumor and tumor-promoting immune cells, such as CD4+ Th1 and regulatory T cells (Tregs), respectively, is assumed to dictate the progression of hepatocellular carcinoma (HCC)." (PMID 34769191, 2021). "During the development of NAFLD-promoted hepatocellular carcinoma, intrahepatic CD4+ T cells are crucial for antitumor surveillance." (PMID 34764874, 2021). "Our results suggested CDC6 expression had strong correlations with tumor purity, infiltrating levels of CD8+ T cells, CD4+ T cells, macrophages, neutrophils and dendritic cells in hepatocellular carcinoma tissues." (PMID 33173413, 2020). "The results of this study showed that solanine inhibited the growth of transplanted hepatoma in mice and reduced the proportion of CD4+CD25+Foxp3+ Treg and the expression levels of Foxp3 and TGFβ mRNA." (PMID 33204731, 2020). "Hoechst and colleagues have shown that CD14+HLA-DR−/low M-MDSCs from hepatocellular carcinoma patients induce suppressive CD4+CD25+Foxp3+ Tregs in a contact-dependent manner when co-cultured with autologous CD3/CD28-stimulated CD4+ T cells." (PMID 32793192, 2020). "In order to observe the effect of solanine on Treg in hepatocellular carcinoma-bearing mice, CD4+CD25+Foxp3+ was used as the marker of Treg in this study." (PMID 33204731, 2020). "In the hepatoma model, treatment with the dual-function vector significantly promoted the activation of NK and CD4+ T cells." (PMID 31849942, 2019). "In patients with chronic hepatitis B infection and hepatocellular carcinoma it was found that the CD4+ CTL also produced IL-10 which inhibited the function of CD8+ CTL." (PMID 30323982, 2018). "A positive correlation of Tregs (CD4+ CD25high and the Foxp3 mRNA) with the tumor stage was also noted in patients with hepatocellular carcinoma." (PMID 27866241, 2017). "The co-culture system permits the daily analysis of HIV-1 and HCV replication in a mixed population of infected human CD4+ T-lymphocytes and hepatoma cells." (PMID 26263487, 2015). "ICAM-1/LFA-1 interactions also appear to drive HIV-1 transmission from infected CD4+ T cells to trophoblasts and from human hepatoma cells to CD4+ T cells." (PMID 22970312, 2012). "To this end, we established a CD4+ T cell/hepatocyte co-culture using a human hepatoma cell line (Huh7.5), stably transfected with the full HCV genome (Huh7.5-FL) or a subgenomic region of HCV (Huh7.5-SG)." (PMID 20730048, 2010). "By using an HCV expressing hepatoma line, Huh7.5-FL, we evaluated the contribution of infected hepatocytes on CD4+ T cell dysfunction." (PMID 20730048, 2010). "It would be interesting to know how the liver Kupffer cells or dendritic cells handle the autophagic hepatoma cells exogenously and present hepatoma cell antigen to CD4+ T and CD8+ T cells in both MHC class II and class I-restricted mechanisms." (PMID 19272170, 2009). "In experimental systems, core expression leads to the development of diverse pathological effects including CD4+ T-cell depletion, liver steatosis, insulin resistance, and hepatocellular carcinoma." (PMID 19505299, 2009). "In a hepatocellular carcinoma case study, all 5 EpiMII-designed epitopes could markedly activate CD4+ T cells in vitro and induce the secretion of interferon-γ and tumor necrosis factor-α." (PMID 42306778, 2026). "Furthermore, by blocking the advantageous antitumor immunity, a subpopulation of suppressive T cells called CD4+CD25+ regulatory T cells (Tregs) add to the immune suppression seen in hepatocellular carcinomas (HCCs) patients." (PMID 40771802, 2025). "Moreover, MitoTEMPO inhibits ROS production, increases intrahepatic CD4+ T lymphocyte counts, and delays the development of hepatocellular carcinoma (HCC) induced by MASLD." (PMID 40584092, 2025).
hepatocellular carcinoma (continued). "This is particularly relevant for immunotherapies that target liver tissue, e.g., hepatocellular carcinoma, to overcome intrinsic liver- as well as tumor-induced tolerance and to elicit antigen-specific effector CD4+ and CD8+ T cells collectively contribute to successful therapies." (PMID 40027262, 2025). "Previous studies have shown that BTLA and PD-1 are co-expressed in human melanoma CD8+ T cells and hepatocellular carcinoma CD4+ T cells, and both BTLA and PD-1 can recruit SH2-containing protein tyrosine phosphatase (SHP)-1 and SHP-2 to suppress T-cell receptor signaling." (PMID 40463377, 2025). "These CD3+CD4+CD56+ T cells might be immunosuppressive, since immunosuppressive CD3+CD4+CD56+CD25+FOXP3+ T cells were identified at a high frequency in hepatocellular carcinoma, and higher infiltration of these cells was inversely correlated with survival." (PMID 38481999, 2024). "The UMAP visualization further elucidated the diversity of cellular subpopulations, highlighting the presence of CD4 + T cells and TAMs, which are pivotal in understanding the immune microenvironment of hepatocellular carcinoma and informing therapeutic development strategies." (PMID 39388011, 2024). "In addition, LINC01060 is predicted as CD4+ T cell-related lncRNA and is involved in the prediction of the prognosis of hepatocellular carcinoma." (PMID 38357948, 2024). "It is known that surgical procedures can induce alterations of peripheral blood lymphocytes, which has been shown for cytotoxic T cells in patients after resection of hepatocellular carcinoma, and for total T cells and CD4 + cells in patients with gastrointestinal cancer." (PMID 38987735, 2024). "It is well known that hepatitis B virus is the main cause of hepatocellular carcinoma, and the synergistic effect of CD4+ T cell-derived exosomes on HBsAb may contribute to the inhibition of hepatocellular carcinoma." (PMID 37153615, 2023). "The immune infiltration analysis of hepatocellular carcinoma showed that NUSAP1 might regulate the immune microenvironment by influencing CD4+ T cells." (PMID 37752167, 2023). "The activation of memory CD4 T-cell-associated genes CST7, CD5L, hsa-miR-23b-3p, and hsa-miR-23a-3p may correlate with the prognosis of hepatocellular carcinoma." (PMID 37139238, 2023). "Finally, the authors also discovered cytotoxic CD4+ T cell subsets using databases for breast, head and neck, and hepatocellular cancer, further supporting the existence of cytotoxic CD4+ T cell subsets among TILs in human cancers." (PMID 36159781, 2022). "Likewise, the primary flavonoid glycoside of G. procumbens leaves, miquelianin, was demonstrated to upregulate HO-1 by activating the ERK-Nrf2 pathway in CD4+ T cells, and human hepatoma HepG2 cells." (PMID 35630834, 2022). "Moreover, CLST was co-enriched with activated CD4+ T cells bearing harmful factors (aCD4) during all stages of hepatitis B virus pathogenesis, which was also verified by our hepatocellular carcinoma data." (PMID 36569318, 2022). "Jinlong capsules may also improve the immune function of patients by increasing the percentage of CD3+, CD4+, natural killer (NK) cells, and the CD4+/CD8+ ratio in patients with hepatocellular carcinoma." (PMID 35341138, 2022). "CD4 + T cells are protective in the development of hepatocellular carcinoma in mouse models." (PMID 34324544, 2021). "Also, CD28−Tim-3+CD4+ T cells from patients with hepatocellular carcinoma were reported to exhibit impaired ability to produce of IL-2 and IFNγ but their possible exhausted status was not ruled out." (PMID 34386013, 2021). "Fuzheng-Qingjie granules can not only induce mitochondria-mediated apoptosis in HepG2 hepatoma cells in vitro but also increase the number of CD4+ T lymphocytes, NK cells, and ratio of CD4+/CD8+ T cells in the peripheral blood of H22 subcutaneous tumor-bearing mice." (PMID 32595757, 2020).
hepatocellular carcinoma (continued). "In this study, the effects of solanine on CD4+CD25+ Treg cells in tumor microenvironment of transplanted hepatocellular carcinoma mice were observed, to study the antitumor effect of solanine and to explore the possibility of solanine in immunotherapy for tumor." (PMID 33204731, 2020). "In addition, tumor-infiltrating lymphocytes, including activated NK cells, resting memory CD4 T-cells, eosinophils, and activated mast cells were significantly correlated with hepatocellular carcinoma survival." (PMID 33049716, 2020). "Hence, we retrospectively selected 74 hepatocellular carcinoma cases and performed immunohistochemical analysis for PD-L1, CD4, CD8, CD276 and SOCS3 for each paraffin-embedded block." (PMID 32742491, 2020). "Previously, we reported that therapy with a dual-function small hairpin RNA (shRNA) vector containing a Pim-3-silencing shRNA (sh-Pim-3) and a TLR7-stimulating ssRNA markedly suppressed the growth of murine hepatoma through activating CD4+ T cells and NK cells." (PMID 31849942, 2019). "The physiological role of the expanded CD4 CTLs remains unclear in humans, however a recent single-cell transcriptome study identified tumor-infiltrating CD4 CTLs in human hepatocellular carcinoma." (PMID 31719197, 2019). "In addition, rNDV-IL2-NP/P had the strongest inhibition of murine hepatoma carcinoma tumors growth, elicited highest degrees of splenocytes CD4+ T and CD8+ T cells, and obviously enhanced animals’ survival rate." (PMID 27736965, 2016). "CD4+ T lymphocyte cells play a “sensing” role in detecting pre-malignant tumor cells and then regulate their eradication, which can hinder the occurrence and development of hepatocellular cancer." (PMID 26057470, 2015). "In addition, high percentages of CD14+HLA-DR−/low M-MDSCs in patients with hepatocellular carcinoma were shown to induce the production of CD4+CD25+Foxp3+ regulatory T cells." (PMID 25436215, 2014). "Initially, the Con A effect is not tumor cell-specific, but as hepatic inflammation proceeds following Con A-mediated destruction and activation, tumor antigens of the hepatoma cells will be processed and presented to the tumor antigen-specific CD4+ T and CD8+ T cells." (PMID 19272170, 2009). "The evaluation reveals that CD4+ T cells are targeted by HIV, while HBV targets the liver with its associated diseases (cirrhosis and hepatocellular carcinoma (HCC))." (PMID 40003989, 2025). "It is noteworthy that in hepatocellular carcinoma (HCC), research by Wang and colleagues has identified an enrichment of double‐positive T cells (expressing both CD4+ and CD8+) in the leading‐edge zone." (PMID 39716897, 2024). "BTLA increases more significantly in circulating CD4+ T cells than in CD8+ T cells in hepatocellular carcinoma (HCC)." (PMID 38785930, 2024). "Furthermore, a significant, positive correlation was detected between the expression of individual KDM3 family members and the infiltration levels of various immune cells, including B cells, CD8+ T cells, CD4+ T cells, macrophages, neutrophils, and dendritic cells, in hepatocellular carcinoma (HCC)." (PMID 39519018, 2024). "Loss of CD4 + T cells promotes progression to HCC in nonalcoholic fatty liver disease and elimination of neutrophil extracellular traps (NETs) may reduce progression to hepatocellular carcinoma in nonalcoholic steatohepatitis." (PMID 37400985, 2023). "Moreover, consistent with the results of cocultured with CD8+ T cells, hepatoma cells (Huh‐7) with HCV core expression presented significantly suppressed cell proliferation activity of activated splenic CD4+ cells by anti‐CD3 antibody compared with GFP expression alone or ISX‐specific shRNAi." (PMID 37316966, 2023). "High PTGES3 expression was related to the infiltration of Th2 subsets of CD4+ T cells and immune checkpoint-related genes in most cancers, especially in hepatocellular carcinoma (HCC)." (PMID 37274225, 2023).